IGFBP3 (insulin like growth factor binding protein 3)
Diseases named in the same sentence as IGFBP3 in open-access papers (continued):
Sharing a sentence is not in itself a finding about the gene and the disease.
cancer (337 papers, 1997 to 2026). A tumor composed of atypical neoplastic, often pleomorphic cells that invade other tissues. "Several studies have reported that lower IGFBP3 levels were associated with a greater risk of various cancers 29-31." (PMID 38169528, 2024). "High circulating concentrations of IGFBP-3 are associated with reduced cancer risk; however, once cancer develops, IGFBP-3 levels in cancer patients drop significantly compared to levels in control groups." (PMID 38137390, 2023). "Differences in circulating IGF-1 and its inhibitors (IGFBP-2 and IGFBP-3) have been associated with the risk of several cancers, thus proposing these indicators as non-invasive biomarkers for cancer risk and prognosis." (PMID 38137390, 2023). "Investigations on cancer risk take into account not only the concentration of IGFs and IGFBPs, but particularly the ratio of IGFs and IGFBP-3." (PMID 36013453, 2022). "Insulin-like-growth factor binding protein-3 (IGFBP3) is an N-linked glycosylated, phosphorylated protein, which has been recognized to regulate cancer progression and metastasis." (PMID 35003355, 2021). "The study was able to note how IGF-I and IGFBP3 levels are associated with risks for possible diseases including cancers." (PMID 32961987, 2020). "The determination of IGFBP3 circulating levels and gene polymorphisms is useful for the assessment of growth disorders and various kinds of cancer." (PMID 30290787, 2018). "As regards IGFBP3, alterations of DNA methylation in the promoter have been associated with degree of expression and with survival rates from various cancer forms in humans." (PMID 29947889, 2018). "Several studies performed in healthy controls, adult GH-deficient patients, and in patients with cancer showed a higher promoter activity (and higher IGFBP3 circulating levels) in AA>AC>CC genotypes." (PMID 30619084, 2018). "Epidemiological studies have yet to show if there are any associations between circulating IGFBP3 concentrations and cancer risk or prognosis." (PMID 29947889, 2018). "In the majority of HCC patients, the inverse association between serum IGFBP3 level and the risk of cancer was observed." (PMID 29702590, 2018). "The AA genotype was associated with higher IGFBP-3 circulating levels, which have been previously shown to be associated with a decreased risk of most cancers." (PMID 30290787, 2018). "Cancer cells acquire resistance against EGFR inhibitor treatment via loss of IGFBP-3, which activates the IGF-1R signaling pathway." (PMID 29445126, 2018). "High levels of circulating IGF-I and low levels of IGFBP-3 are reportedly associated with an increased risk of several common cancers, including those of the prostate, breast, colon, and lung." (PMID 29113370, 2017). "The positive association between BMI and IGFBP-3 was previously observed in cancer-free men in the ProtecT study." (PMID 28646365, 2017). "Circulating concentrations of insulin-like growth factor (IGF-1) and IGF-binding protein 3 (IGFBP-3) are linked to a higher risk of common cancers." (PMID 29194365, 2017). "Circulating concentrations of IGF‐I and IGFBP‐3 have been associated with risk of type 2 diabetes, cardiovascular diseases, cancer, and mortality in epidemiological studies." (PMID 27329260, 2016). "This study sought to investigate the role of IGFBP-3 in the adhesion of cancer and vascular endothelial cells to the ECM and the underlying molecular mechanism, with a focus on IGF-1 dependency." (PMID 25945837, 2015). "Epidemiological studies have confirmed that genetic variations of IGF-I and IGFBP-3 are associated with an increased risk of common cancers, including PCa, colorectal cancer, lung cancer and breast cancer." (PMID 24586243, 2014). "Epidemiological studies show that high levels of IGF1 and low levels of IGFBP-3 are associated with an increased risk for several common cancers, including prostate, breast, lung, and colorectal cancer." (PMID 24905466, 2014).
cancer (continued). "Recently, the association between the IGF-I and IGFBP-3 polymorphisms and the risk of various cancers, including PCa, has been clarified by many genetic approaches using single amino acid mutations and by molecular epidemiological studies." (PMID 24586243, 2014). "Excess autocrine/paracrine production of IGF-1 and IGF-2 and/or low IGFBP3 levels are associated with an increased cancer risk of several cancers including breast, endometrial and bladder." (PMID 23826179, 2013). "Until 2009, there were several studies evaluating associations between the IGFBP3 polymorphisms and cancer risk in diverse populations and in multiple types of cancer, but their outcomes have been contradictory." (PMID 23527244, 2013). "In vitro assays of prostate cell lines derived from these mouse lines also indicated a more aggressive cancer phenotype in IGFBP3 deficient cells." (PMID 24019942, 2013). "But practically, there were also some epidemiological studies showing null association between circulating IGF-1 and IGFBP-3 levels and cancers." (PMID 23185474, 2012). "IGFBP-3 is supposed to have growth-inhibiting properties and one would, thus, expect that high IGFBP-3 concentrations are inversely associated with cancer risk." (PMID 22315049, 2012). "Above on, an elevated level of circulating IGF-1 and/or a lower level of IGFBP-3 was related to the increased risk of cancers, and this was supported by some studies in breast, prostate and colorectal cancers." (PMID 23185474, 2012). "The level of IGFBP3 in serum, in some situations, suppresses the mitogenic action of IGFs, and is inversely associated with cancer risk." (PMID 22347413, 2012). "Epidemiological studies have shown that increased levels of circulating IGF-I or increased IGF-I relative to IGFBP-3 are associated with a higher risk of developing several forms of cancer, including prostate and breast cancers." (PMID 20885914, 2010). "For example, IGFBP3 expression in cancer cells and in the circulation is associated with less malignant growth and decreased cancer risk in breast, prostate and other cancers." (PMID 19158946, 2009). "Similar to our findings for EGFR, the IGFBP3 regions associated with modified risk appear to be functionally important in cancer." (PMID 19603096, 2009). "Several studies suggest an inverse association between plasma IGFBP-3 and risk of cancer in a number of organs." (PMID 18498652, 2008). "High plasma levels of IGF-I and low levels of IGFBP-3 are associated with the development of prostate, colorectal, and premenopausal breast cancer." (PMID 17533398, 2007). "High expression of IGFBP3 has been associated with invasiveness and poor prognosis in other cancer types." (PMID 17181856, 2006). "In any case, the level of LD in the 5′ region of the gene is so high that an association study approach alone will not be able to single out one particular variant as that causing variation in IGFBP-3 levels and, possibly, cancer risk." (PMID 16404426, 2006). "In this study, adjusting for IGFBP-3 increased the OR for the association of IGF-I with premenopausal cancers." (PMID 15756268, 2005). "The various reports of strong and sometimes conflicting associations between IGFBP-3 concentrations and cancer risk indicate that it would be of considerable interest to measure individual forms of IGFBP-3." (PMID 15756268, 2005). "In addition, cancer risk increases with a decrease in IGFBP3 and an increase in insulin‐like growth hormone levels." (PMID 38468402, 2024). "Additionally, many studies verified that IGFBP-3 inhibition by DNA methylation is associated with cancer development and resistance to chemotherapy and radiotherapy." (PMID 39272080, 2024). "This suggests that IGFBP3-mediated growth-inhibitory signals may cause the upregulation of Akt phosphorylation in ME-treated cancer cells." (PMID 36864505, 2023).
cancer (continued). "Moreover, we found an association between these biomarkers and IGF-1/IGFBP3, which enhances their credibility as biomarkers for cancer detection in high-risk tumors." (PMID 37108716, 2023). "IGFBP-3 has been associated with different cancers, showing both promoting and inhibiting actions." (PMID 35356065, 2022). "Abnormal expression or malfunction of IGFBP3 is associated with cancer development and progression." (PMID 33712045, 2021). "Among the IGF signal-linked genes identified in the present study, PRDM1 downregulated expression of IGFBP3 and thus the effects of IGFBP3 suppression on the ERK1/2 signal as central downstream signaling kinases of IGF-RAS-linked pathways were assessed in ribosome-inactivated cancer cells." (PMID 33972671, 2021). "Besides, circulating levels of IGFBP-3 are associated with increased risk of some cancers, but the results vary from site to site." (PMID 33414813, 2020). "Moreover, the evidence for an association between circulating IGFBP-3 and either cancer risk or prognosis in different cancer types is inconsistent." (PMID 32093285, 2020). "Moreover, high IGF1 concentrations have been implicated in cancer, whereas IGFBP3 has a protective effect." (PMID 30759961, 2019). "In addition, there were multiple genes induced that are involved with cell and organelle structure and function (PNCK, UBD, CDH2, HERC5) and importantly, genes associated with the prostate, AR (MMP7, CDH2, ENO2, IGFBP3) and cancer (IFIT3, IFI44L)." (PMID 29416764, 2018). "The association between HPV infections and IGF levels has not been extensively explored in cervical neoplasia; nevertheless, a growing number of studies have recently demonstrated an association between serum levels of IGFs and IGFBP-3 and increased risk for various cancers." (PMID 25333772, 2014). "Associations between IGF-1, IGFBP-3, and cancer risk vary by cancer site." (PMID 24829560, 2014). "Serum IGF-1 and IGFBP-3 concentrations can be measured easily and could be of value as indicators of cancer risk." (PMID 24339922, 2013). "Early life body size and circulating levels of IGF-1 and IGFBP-3 have been linked to increased risks of breast and other cancers, but it is unclear whether these exposures act through a common mechanism." (PMID 22894543, 2012). "Different studies on the risk of prostate, breast, colorectal, lung, and thyroid cancer suggest that high circulating IGF-I levels are related to an elevated risk of cancer, whereas high levels of insulin-like growth factor binding protein type 3 (IGFBP-3) levels are associated with a reduced risk." (PMID 22518126, 2012). "Excess GH causes an elevated IGF-I to IGFBP-3 ratio, which is expected to increase cancer risk." (PMID 22518126, 2012). "Indeed, it has been reported that high IGF-1 and low IGFBP-3 levels in serum increase the risk of cancer." (PMID 22429812, 2012). "Besides these increased IGFBP-5 mRNA levels have been proved to be associated with a poor outcome for the patients who have positive lymph nodes and high circulating concentrations of IGFBP-3 is associated with a lower cancer risk from clinical trail." (PMID 20003295, 2009). "Further studies measuring intact, fragmented, and total IGFBP-3 would help to identify whether this molecule is a cancer risk factor, a preventive factor, or both." (PMID 18471292, 2008). "When we performed the same analysis by using the haplotype block that spans the 5′ end of the gene and includes rs2162679 and rs35767, the same haplotype that is associated with reduced cancer risk appeared also to be strongly associated with decreased IGFBP-3 levels (P<0.0001)." (PMID 16404426, 2006). "It is thought that a relatively high IGFBP-3 concentration may indirectly reduce cancer risk by binding a greater proportion of circulating IGF-I, thereby reducing its bioavailability and thus inhibiting its mitogenic effects." (PMID 15756268, 2005).
cancer (continued). "In a recent systematic review and meta-regression analysis of 21 studies, we determined the associations between circulating IGF-I and IGFBP-3 levels and cancer risk, and demonstrated that the patterns of association differed between smoking and nonsmoking-related cancer." (PMID 15354219, 2004). "Across the general population, there are wide interindividual variations in IGF-I and IGFBP-3 concentrations, which may impact upon cancer risk." (PMID 15354219, 2004). "Furthermore, considering the mitogenic nature of IGF-1, its interaction with receptors can be regulated by IGFBP-3, and upregulation of IGF-1/IGFBP-3 or a lower level of IGFBP-3 may increase the risk of cancer." (PMID 33815885, 2021). "Thus, collapse of vimentin architecture and subsequent modification of its assembly/disassembly may be the mechanism underlying IGFBP-3-mediated regulation of cancer cell migration and invasion." (PMID 33801272, 2021). "Besides, promoter methylation of IGF-1R, IGF-1, IGF-II, and especially IGFBP-3 in various regions could be associated with cancer prognosis." (PMID 33768092, 2021). "Some cell culture studies have shown that IGFBP3 plays a vital role in cell survival or apoptosis in various microenvironments; meanwhile, several clinical studies have indicated that variations in IGFBP3 levels are associated with an altered risk for certain common cancers." (PMID 30290787, 2018). "However, specific associations between hyperglycemia, insulin, IGF-1, IGFBP3 and the risk of cancer among people with type 2 diabetes remain unclear." (PMID 23405181, 2013). "Thus, the association between IGF1, IGF2, and IGFBP3 and cancer risk could be evaluated on the molecular level." (PMID 22347413, 2012). "Whereas some authors have hypothesised that the relative levels of IGF-I to IGFBP-3 may be important for cancer risk, the absolute quantities (reflecting total body stores) may be more pertinent, remembering that IGFBP-3 circulates in molar concentrations considerably (five-fold) greater than IGF-I." (PMID 15354219, 2004). "In recent years, the roles of SERPING1 and IGFBP3 have garnered increasing attention as potential therapeutic targets for various diseases, including autoimmune disorders and cancers." (PMID 40377287, 2025). "Loss of expression of the IGFBPs, IGFBP3 and IGFBP4, has previously been linked with resistance to gefitinib in other cancer types and IGFBP-3 is frequently concomitantly overexpressed with EGFR in ESCC." (PMID 40615716, 2025). "On the other hand, IGFBP3 is involved in cell proliferation, apoptosis, and tissue remodeling, making it a key player in cancer progression, tissue repair, and metabolic diseases." (PMID 40377287, 2025). "IGFBP-3, its primary binding protein, regulates these effects and plays a dual role in either promoting or inhibiting cancer progression." (PMID 40493660, 2025). "TGF-β initiates the autocrine activation loop that produces insulin-like growth factor binding protein-3 (IGFBP-3) to promote cancer invasion and migration." (PMID 40248695, 2025). "This promotes positive feedback on IGFBP-3 expression, and continual IGFBP-3 overexpression promotes cancer progression." (PMID 41226289, 2025). "IGFBP3, a protein that exhibits multiple regulatory functions, has elevated expression in multiple cancer types and assumes a decisive role in the malignant advancement of tumors." (PMID 38326861, 2024). "Insulin-like growth factor binding protein-3 (IGFBP-3) is a multifunctional protein that participates in the pathophysiology of several human diseases, including cancer." (PMID 39272080, 2024). "Insulin-like growth factor binding protein-3 (IGFBP-3) with its molecular framework can serve as a new line of antiangiogenic cancer drugs." (PMID 38841622, 2024).
cancer (continued). "The insulin-like growth factor (IGF) axis, particularly that of IGF-1 and its binding protein, insulin-like growth factor-binding protein-3 (IGFBP-3), is another area of interest in cancer research." (PMID 39200386, 2024). "The proteolysis of IGFBP-3 is a crucial process, particularly since IGFs, if released in excess, play a role in pathologies such as cancer, where they promote cellular proliferation." (PMID 39585162, 2024). "Our present results revealed that CAFs strongly promote cancer progression and selectively suppress IGFBP3 expression via GATA1 transcriptional downregulation, which results in cisplatin resistance in OSCC." (PMID 38169528, 2024). "Studies show major discrepancies in this regard, while the majority of studies show lower circulating levels of IGFBP-3 in several cancers including hepatocellular carcinoma, esophageal cancer, and CRC." (PMID 38137390, 2023). "And for the majority of the cancers, IGFBP3, IGFBP4, IGFBP5, IGFBP6 and IGFBP7 were significantly positively associated with stromal, immune as well as ESTIMATE scores including COAD, PCPG, PRAD, READ and STAD." (PMID 37088808, 2023). "IGFBP3 belongs to a class of intracellular molecules with numerous regulatory functions that play various roles in many cancers." (PMID 35966888, 2022). "It is shown that anti-tumor activity of melatonin in prostate cancer is mediated by IGF pathway in such a way that IGFBP3 is upregulated but IGF1R is downregulated after treatment of cancer cells by melatonin." (PMID 36581900, 2022). "IGFBP-3, enriched in hypoxic cancer-cell-derived EVs, is a factor known to induce a subpopulation of CD38high MDSC cells with an even more immature phenotype compared to MDSCs lacking CD38." (PMID 36010994, 2022). "In an independent manner, IGFBP-3 is able to regulate the survival and proliferative activity of healthy and cancer cells." (PMID 35115550, 2022). "IGFBP3 is a potent antiproliferative and proapoptotic factor in cancer cells whose biological action is mediated through interactions with a variety of binding partners on the cell surface and within cells via multiple signaling pathways." (PMID 35154570, 2022). "Accordingly, patients with malignant tumors (4.04 ± 0.14) produced higher level of IGFBP-3 in serum compared to patients with benign tumors (2.50 ± 0.15) (P < 0.0001)." (PMID 36713521, 2022). "As a multifunctional protein, IGFBP3 can impact on several molecular mechanisms that regulate cell survival or apoptosis, especially in the context of cancer." (PMID 36409444, 2022). "In another study, it was seen that melatonin treatment of breast cancer cells causes reduced VEGF-A protein expression and increased IGFBP-3, IGFPB-6, IGF-1, IGF-1R proteins in those cells and results in suppression of cancer cell growth." (PMID 36581900, 2022). "The insulin-like growth factor binding protein-3 gene (IGFBP3, OMIM*146732) influences lipid parameters in adolescents and cancer susceptibility in the general population." (PMID 36143124, 2022).